IGF1R (insulin like growth factor 1 receptor)
Diseases named in the same sentence as IGF1R in open-access papers (continued):
Sharing a sentence is not in itself a finding about the gene and the disease.
breast cancer (continued). "Our findings are consistent with previous reports identifying ZEB1 as a downstream target of IGF1R, potentially assisting EMT processes in breast cancer cells." (PMID 25749031, 2015). "In breast cancers treated with EGFR inhibitors, IGF1R can replace EGFR in heterodimers to confer resistance." (PMID 25629162, 2015). "IGF-1R known as an oncoprotein is directly suppressed by HRD1, and downregulation of HRD1 increases IGF-1R expression levels in breast cancer." (PMID 26536657, 2015). "Breast cancer patients, especially HR+, HER2-, and tumor patients with a Ki-67≥14%, who had a better score for IGF-1R expression had a higher survival." (PMID 25867717, 2015). "IGF-1R are widely expressed on normal and neoplastic cells, and an IGF-1 autocrine loop was described in ovarian and breast cancer cells." (PMID 26510816, 2015). "Previous studies have shown that inhibiting the PI3K/AKT pathway can lead to the up-regulation and over-activation of RTKs, such as HER3 (ErbB3), IGF-1R or IR, aimed at maintaining the PI3K pathway in equilibrium in breast cancer or NSCLC." (PMID 25654224, 2015). "It has been reported that miR-335 suppresses breast cancer metastasis by targeting SOX4 and Tenascin C, small cell lung cancer metastasis by targeting IGF1R and RANKL, and induces apoptosis of breast cancer cells by regulating ERα, IGF1R, SP1, and ID4." (PMID 26098312, 2015). "Among the genes amplified in the focal regions were a cluster of HOX genes (HOXA7, HOXA9, HOXA10, HOXA11) on 7p15, AKT1 (14q32.33), IGF1R (15q26.3), ERBB2 and NEUROD2 (17q12), all of which have been reported in primary breast cancers." (PMID 24489661, 2014). "Therefore, it is particularly worth investigation whether the epigenetic modifications observed in trastuzumab-resistant cells are also outcomes of upstream IGF1R signaling, which will eventually form a regulatory circuit to facilitate the establishement of trastuzumab resistance in breast cancers." (PMID 24571711, 2014). "In contrast, mutant BRCA1 proteins lack transcriptional activity and are impaired in their ability to suppress the IGF1R promoter, with resulting increases in IGF1R mRNA and IGF binding in mammary tumors." (PMID 24904527, 2014). "Here, we demonstrate that suppressed expression of miR-375, which is a tumor suppressor targeting IGF1R, contributes to trastuzumab resistance of HER2-positive breast cancer cells." (PMID 24571711, 2014). "The insulin-like growth factor receptor (IGF1R) is another important gene that we have shown to be differentially expressed in WBC from the carriers and breast cancer patients." (PMID 25403427, 2014). "We identified downregulated CARs in vicinity or overlapping the oncogenes IGF1R, MYLK, the breast cancer drug target OGT (O-GlcNAc transferase), and the breast cancer-related cyclin CCNL1." (PMID 25264628, 2014). "Inhibition of IGF-1R or EGFR-3 restored hormonal dependency and the effects of hormonal therapy on the breast cancer cells with PTEN-knocked down." (PMID 25051360, 2014). "On the other hand, 5 genes were differentially expressed with significant difference between the breast cancer patients and carriers, BRCA1 (p = 0.03), BIRC5 (p = 0.035), CCND2 (p0.034), ATM (p = 0.012) and IGF1R (p = 0.025)." (PMID 25403427, 2014). "A potential panel of markers for molecular imaging, consisting of EGFR, IGF1-R, FGFR2, CD44v6, CAXII, GLUT1, and CD44v6 was positive in 77% of male breast cancers, comparable to female breast cancers." (PMID 23308200, 2013). "Rp1 inhibited proliferation of human breast cancer cells such as MCF-7 and MDA-MB-231 through suppression of IGF-1R/pAkt pathway, pAkt of which is also suppressed by Rh2 and aPPD." (PMID 23889969, 2013). "Our data support the notion that IGF-1R is a marker of stemness, and IGF-1R and its downstream PI3K/Akt/mTOR pathway are attractive targets for therapy directed against breast cancer stem/progenitors." (PMID 23663564, 2013).
breast cancer (continued). "The combination of IGF1R antagonists with TAM also induced high levels of apoptosis in BT474 and MCF-7 breast cancer cell lines." (PMID 23476711, 2013). "For example, hormone receptors (ER and PR), growth factor receptor (HER2, EGFR, and IGF-1R), and angiogenic factors (VEGFR, integrin αvβ3) have been adopted as imaging targets to detect/stage the breast cancer and monitor treatment efficacy." (PMID 23533377, 2013). "The insulin-like growth factor 1 tyrosine kinase receptor (IGF-1R) and the chemokine G-protein coupled receptor, CXCR4 have been shown to play an important role in breast cancer metastasis." (PMID 23320409, 2013). "A specific inhibitor of the IGF-1R, picropodophyllin suppressed phospho-AktSer473 and preferentially decreased ALDH+ BCSC populations of human breast cancer cells." (PMID 23663564, 2013). "In conclusion, we found that expression of individual growth factor receptors (IGF1-R, FGFR2, and MET) and CD44v6, CAXII in male breast cancer is different compared to female breast cancer." (PMID 23308200, 2013). "In a recent report by Jones and colleagues, recurrence of breast cancer was observed in 16% of inducible IGF-1R transgenic mice upon the discontinuation of doxycycline and the recurrence involved IGF-1R-reactivation and IGF-1R-independent mechanisms." (PMID 23663564, 2013). "In our study population of 133 cases of male breast cancer, we found 4 cases (3.0%) expressing HER2, 15 cases (11.4%) EGFR, 6 cases (4.5%) MET, 16 cases (12.1%) FGFR2, and 50 cases (38.5%) IGF1-R." (PMID 23308200, 2013). "We found that expression of IGF1-R was present in 38.5%, FGFR2 in 12.1%, EGFR in 11.4%, HER2 in 3.0%, and MET in 4.5% of male breast cancers." (PMID 23308200, 2013). "Our previously proposed panel consisting of CD44v6, EGFR, HER2, IGF1-R, and GLUT1 for imaging of female breast cancer was significantly less sensitive for imaging of male breast cancer (female breast cancer 79.3% vs. male breast cancer 69.1%, p = 0.025)." (PMID 23308200, 2013). "More importantly, IGF-1R could serve as a novel marker for a particular population of cancer cells with stem/progenitor features within breast cancer since IGF-1R high-expressing human breast cancer cells displayed the capacity for mammosphere formation in vitro and tumorigenicity in vivo." (PMID 23663564, 2013). "Compared to female breast cancer, IGF1-R was more frequently expressed in male breast cancer (p<0.001), while MET and FGFR2 were less frequently expressed (both p<0.001) in male breast cancer." (PMID 23308200, 2013). "Furthermore, it has been reported that IGF-1R expression was positively correlated with a shorter disease-free survival in triple negative breast cancer, the particular subtype with the highest rate of recurrence and higher percentage of BCSCs than other breast cancer subtypes." (PMID 23663564, 2013). "Compared to female breast cancer, IGF1-R and carbonic anhydrase 12 (CAXII) were more frequently and CD44v6, MET and FGFR2 less frequently expressed in male breast cancer." (PMID 23308200, 2013). "Compared to female breast cancer, IGF1-R expression was higher and MET and FGFR2 expression lower in male breast cancer." (PMID 23308200, 2013). "Our findings suggest that IGF-1R and its signaling via PI3K/Akt/mTOR pathway are attractive targets for therapy directed against breast cancer stem/progenitors." (PMID 23663564, 2013). "This was coupled with greater breast cancer cell Akt and ERK1/2 phosphorylation, as well as enhanced IGF-1R activation." (PMID 23880059, 2013). "On the other hand IGF-1R gene copy number gain was identified in some tumor types, such as wild-type GIST, breast cancer and NSCLC." (PMID 22415797, 2012). "For instance, IGF1R and IRS1 were identified as predictive markers of tamoxifen response in patients with early breast cancer." (PMID 22343619, 2012). "The gene expression and protein expression of IGF-1R, PDGFA, NGF, NF-κB and JNk-2 in breast cancer cells was inhibited by UTI and TXT." (PMID 22217202, 2012).
breast cancer (continued). "UTI and TXT down-regulate the expression of mRNA and protein of IGF-1R, PDGFA, NGF, NF-κB, and JNk-2 in breast cancer cells and xenografted breast tumors." (PMID 22217202, 2012). "The authors demonstrated that trastuzumab-mediated growth inhibition was lost in breast cancer cells that overexpressed both HER2 and IGF1R." (PMID 22295219, 2011). "To date, the effect of blocking oncogenic IGF-1R and EGFR signaling have been studied more extensively in breast cancer cell lines." (PMID 21776391, 2011). "The genes downregulated in PPP tolerant cell lines were siRNA silenced in non-tolerant cells Line2, Line3, the melanoma cell line BE and breast cancer cell line MCF7, all known to express IGF-1R and to be responsive to PPP." (PMID 21423728, 2011). "To date, the effect of blocking oncogenic IGF-1R and EGFR signaling have been studied more extensively in breast cancer lines." (PMID 21776391, 2011). "An antibody, αIR3, directed against the IGF receptor, IGF1R, blocked IGF activity and tumour growth in xenograft models of human breast cancer, but the antibody had some agonist activity and cross-reactivity with the insulin receptor." (PMID 19536088, 2009). "In breast cancer, IGF-1 expression is elevated in the serum of patients and the IGF-1R is frequently over-expressed and is a prognostic indicator of tumor recurrence and reduced patient survival." (PMID 19534786, 2009). "In support of this, combined inhibition of EGF-R and IGF-1R by Gefitinib (Iressa) and AG1024, respectively, resulted in additive to synergistic inhibition of growth and induction of apoptosis in breast cancer cell lines." (PMID 19784388, 2008). "In this study, AG1024 and gefitinib were used to cotarget IGF-1R and EGFR activity in several human breast cancer cell lines that express IGF-1R similarly but present different levels of EGFR." (PMID 15987464, 2005). "AG1024 (an inhibitor of IGF-1R) was used with gefitinib for treatment of MDA468, MDA231, SK-BR-3, and MCF-7 breast cancer lines, which express similar levels of IGF-1R but varying levels of EGFR." (PMID 15987464, 2005). "For example, while FolTAC-dual effectively targets EGFR and HER2 in resistant HER2+ breast cancer, compensatory signaling through other tyrosine kinases or pathways, such as MET or IGF-1R, may emerge over time." (PMID 41038820, 2025). "In our previous study, we reported that the presence of IGF-1R at the Golgi apparatus was more evident in migratory than nonmigratory breast cancer cell lines." (PMID 39608716, 2024). "Inhibition of IGF1R and its downstream kinases Akt and Erk1/2 activation/Inhibition of epithelial-mesenchymal transformation (EMT) transcription factors Snail and Slug expression in human MD-MB-231 breast cancer cells (TNBC cell line)." (PMID 39712006, 2024). "IGF1R targeting in breast cancer cells using small interfering RNA (siRNA) approaches not only decreased tumor growth in syngeneic mice but also triggered the features of an immune response." (PMID 38892104, 2024). "In addition, an integrated database for exosome-based biomarker discovery (ExoBCD) evidenced IGF1R and FRS2 as the most promising prognostic circulating biomarkers for clinical use in breast cancer." (PMID 38892104, 2024). "For example, breast cancer cells exposed to ALA accumulate immature insulin-like growth factor 1 receptor (pro-IGF-1R) in the cytoplasm, indicating that IGF-1R is not properly positioned on the cell membrane and is thus inactive." (PMID 39199143, 2024). "In the insulin-responsive 4T1 mouse model of breast cancer, the IGF1R/IR inhibitor BMS-536924 inhibited tumour growth, without significant hyperglycemia." (PMID 36920947, 2023). "This study identified IGF1R SNVs rs3743259 and rs3743258 as potential predictive markers for worse pathological response on neoadjuvant chemotherapy in patients with HER2-negative breast cancer." (PMID 38136416, 2023). "Both IGF-1R/PI3K/AKT/mTOR and Hippo pathways are crucial for breast cancer stem cells (BCSCs)." (PMID 37081542, 2023).
breast cancer (continued). "At the tissue level, a higher expression level of IGF1R but no change in IRS2 expression level was found in the negative HER2-breast cancer of patients with T2DM compared to non-diabetic counterparts." (PMID 37510134, 2023). "Aberrations of fibroblast growth factor receptors (FGFRs), c-Met, and insulin-like growth factor 1 receptor (IGF1R) are frequently found in urothelial carcinoma, hepatocellular carcinoma (HCC) and breast cancer, respectively." (PMID 37255594, 2023). "The IGF-1R localizes at the cell membrane, in the cytoplasm and within the nucleus in normal breast tissue and the intracellular localization of the IGF-1R has prognostic significance for breast cancer." (PMID 36556357, 2022). "In addition, luminal A and luminal B patients with a high expression of IGF1R and a low expression of IGF2R had significantly higher survival rates than patients with other types of breast cancer." (PMID 36330486, 2022). "In order to further clarify the relationship of diabetes mellitus with the occurrence and development of breast cancer, the expressions of IGF-1R and Ki-67 were detected in breast cancer tissues of patients with/without diabetes mellitus." (PMID 35035440, 2022). "In addition to breast cancer, BRCA1 was identified as a transcriptional repressor of the IGF1R gene in prostate and endometrial cancer cells." (PMID 35432218, 2022). "Here, in the present study, we identified the regulation of the FoxO signaling pathway via the modulation of four genes i.e. MDM2, STAT3, IGF1R, and GRM1 which could support the functioning of the PI3K-Akt and EGFR signal against breast cancer pathogenesis." (PMID 36686654, 2022). "Moreover, they found that miR-940, miR-451a/miR-16-5p, and miR-17-3p target PTEN, IGF1R, and SRC mRNA, respectively, whose aberrant signaling was described as a mechanism involved in trastuzumab resistance of breast cancer cells." (PMID 36358746, 2022). "To prove whether GASP1 regulates IGF1R stability, we treated breast cancer cells with protein synthesis inhibitor CHX and then performed western blot analysis to evaluate the protein expression of IGF1R upon GASP1 knockout or overexpression." (PMID 36042202, 2022). "These current findings establish a potential IGF-1-mTORC1-SRPK2-FASN axis in breast cancer, which could be a potential therapeutic target for cancers that overexpress FASN and components of the IGF-1R pathway." (PMID 36096767, 2022). "Meanwhile, IGF/IGF1R pathway also up-regulates GASP1 expression via the activation of the PI3K/AKT pathway, forming a vicious self-augmenting feedback loop propelling the progression of breast cancer and decreasing sensitivity to paclitaxel." (PMID 36042202, 2022). "Similarly, miR-520b promoted doxorubicin sensitivity in breast cancer cells through downregulation of IGF-1R, i.e., abrogating tumor development, metastasis, and resistance to chemotherapy induced by IGF-1R." (PMID 36017326, 2022). "The results showed that overexpression or knockout of GASP1 did not change the mRNA level of IGF1R in breast cancer cells, suggesting that GASP1 regulates IGF1R expression at the post-transcriptional level." (PMID 36042202, 2022). "All breast cancer cells, including Her2+ and triple negative cells, were observed to exhibit high expression of IGF-1R." (PMID 35399718, 2022). "The proliferation and survival of HER2-positive breast cancer cells are inhibited by negative feedback inhibition of IGF2/IGF-1R/IRS1." (PMID 36210846, 2022). "To determine how reduced IGF1R impacts tumor phenotype in human breast cancers, we used weighted gene co-expression network analysis (WGCNA) of Molecular Taxonomy of Breast Cancer International Consortium (METABRIC) patient data to identify gene modules associated with low IGF1R expression." (PMID 36568144, 2022).
breast cancer (continued). "We performed a similar analysis for IGF1R expression using a different human breast cancer dataset, the Molecular Taxonomy of Breast Cancer International Consortium (METABRIC) database, with a focus on correlations between IGF1R expression and PAM50 subtype, as well as probability of survival." (PMID 35784559, 2022). "While emerging evidence suggests a role for nuclear IGF-1R in breast cancer, it remains to be seen whether IGF-1R within this subcellular compartment can serve as a prognostic marker in breast cancer." (PMID 36556357, 2022). "Breast carcinoma cells engineered to overexpress the IGF-1R become resistant to the ER targeting drugs tamoxifen and fulvestrant, and xenograft tumors derived from tamoxifen-resistant breast carcinoma cell lines express increased phosphorylated IGF-1R." (PMID 36556357, 2022). "Breast carcinoma cell lines exhibit more aggressive, migratory behavior when stimulated with IGF-1 or when overexpressing IGF-1R in vitro, while knockdown of IGF-1R expression impairs colony formation and invasion." (PMID 36556357, 2022). "A functional interaction between the IGF1R and CXCR4 was documented in breast cancer cell lines where CXCR4 and IGF1R directly interacted at the cell membrane, thereby inducing IGF1-evoked CXCR4 transactivation and cell migration independently of its cognate ligand CXCL12." (PMID 34440844, 2021). "Collectively, we demonstrate that the IGF2/IGF-1R/IRS1 signaling is aberrantly activated in Herceptin-resistant breast cancer via disruption of the FOXO3a-miRNA negative feedback inhibition." (PMID 33976188, 2021). "In the absence of the target in hormone resistant breast cancer, IGF1R mAb would be expected to be ineffective." (PMID 33429867, 2021). "In summary, we discover a FOXO3a-miRNA negative feedback inhibition loop to control the IGF2/IGF-1R/IRS1 signaling in HER2-positive breast cancer cells sensitive to Herceptin." (PMID 33976188, 2021). "We discover a negative feedback inhibition of IGF2/IGF-1R/IRS1 signaling in HER2-positive breast cancer cells to maintain basic cell survival and proliferation." (PMID 33976188, 2021). "Furthermore, miR-148a-3p can depress cell proliferation by dampening functional expression of IGF1R and IRS1, whose signaling is crucial in luminal breast cancer subtype." (PMID 32085669, 2020). "IGF-1 receptor (IGF-1R) expression correlates with poor survival and is thought to have a possible role as a prognostic marker, with higher concentrations of IGF-1 noted in the serum of breast cancer patients." (PMID 32792532, 2020). "The stimulatory effect of endogenous hyperinsulinemia on breast cancer progression has been modeled through the use of a transgenic mouse model (MKR), in which a kinase-inactive form of the IGF1R is overexpressed in skeletal muscle under the muscle creatine kinase promoter." (PMID 33604295, 2020). "Patients with ER+, IGF‐1R‐positive breast cancer without p‐IGF‐1R/InsR staining (n = 242) had tamoxifen benefit (HR 0.41, p = 0.0038), while the results for p‐IGF‐1R/InsR‐positive patients (n = 125) were not significant (HR 0.95, p = 0.3)." (PMID 31490549, 2020). "The IGF1 receptor (IGF1R), which mediates the biological actions of IGF1 and IGF2, exhibits potent antiapoptotic and cell-survival activities and is regarded as a key player in breast cancer etiology." (PMID 32391121, 2020). "In addition, Src (SRC), VEGFR2 (KDR), IGF1R and PI3Kγ (PIK3CG) have already been successful targets in breast cancer therapy." (PMID 33246450, 2020). "Nuclear IGF-1R is more pronounced in cancer cell lines, including breast cancer, prostate cancer and sarcoma cells, compared to non-transformed cells." (PMID 33584548, 2020). "In addition, high IGF1R expression and elevated circulating IGF1 levels were correlated with improved response to IGF1R-targeted therapies in clinical trials for non-breast cancers." (PMID 32391121, 2020).